GH2 (growth hormone 2)
Description:
Plays an important role in growth control. Its major role in stimulating body growth is to stimulate the liver and other tissues to secrete IGF1. It stimulates both the differentiation and proliferation of myoblasts. It also stimulates amino acid uptake and protein synthesis in muscle and other tissues.
Synonyms: GH-V; GHV; GHL; hGH-V; GHB2
Tractability: Antibody: its Gene Ontology location is reachable by antibodies, with high confidence; UniProt places it where antibodies can reach, with medium confidence; UniProt predicts a signal peptide or a membrane-spanning region.
Gene: Protein-coding gene on chromosome 17 (63,880,215 to 63,881,944, reverse strand). Ensembl gene ENSG00000136487.
Subcellular location: Secreted
Pathways (Reactome):
Immune System: Growth hormone receptor signaling; Prolactin receptor signaling
Gene Ontology:
Molecular function: growth factor activity; growth hormone receptor binding; hormone activity
Biological process: animal organ development; growth hormone receptor signaling pathway; positive regulation of receptor signaling pathway via JAK-STAT; response to nutrient levels
Cellular component: endosome lumen; extracellular region; cytoplasm; endomembrane system; vesicle
Genetic constraint (gnomAD): Loss-of-function variants: 17 observed, 25.67 expected, observed/expected ratio (o/e) 0.66, 90% interval 0.45 to 0.99. The upper end of that interval is the gene's LOEUF score, 0.99, which puts it in group 4 of 6, group 1 being the genes least tolerant of losing a copy. Missense variants: 305 observed, 279.82 expected, observed/expected ratio (o/e) 1.09, 90% interval 0.99 to 1.2. Synonymous variants: 126 observed, 121.74 expected, observed/expected ratio (o/e) 1.03, 90% interval 0.89 to 1.2.
Homologues: Orthologues: chimpanzee GH2 (98% identical), pig GH1 (64% identical), dog GH1 (63% identical), rabbit GHB1 (63% identical), mouse Gh (61% identical), rat Gh1 (60% identical), guinea pig Gh1 (59% identical), tropical clawed frog gh1 (49% identical), tropical clawed frog gh2 (41% identical), zebrafish gh1 (35% identical). Paralogues in human: GH1 (93% identical), CSH2 (80% identical), CSH1 (80% identical), CSHL1 (76% identical), PRL (23% identical).
Diseases named in the same sentence as GH2 in open-access papers:
GH2 is named in the same sentence as 23 diseases in open-access papers, as found by Europe PMC text mining. Sharing a sentence is not in itself a finding about the gene and the disease. The quoted sentences say what the papers report.
Insulin resistance (6 papers, 2017 to 2026). Increased resistance towards insulin, that is, diminished effectiveness of insulin in reducing blood glucose levels. "Placental growth hormone variant (GH2) is secreted into maternal circulation to promote a state of mild insulin resistance." (PMID 37049394, 2023). "Whilst the exact mechanism by which hPL affects glucose homeostasis remains unknown, GH2 has been shown to trigger severe insulin resistance in an animal model, suggesting that increased levels of GH2 post-fortification may place women at increased risk of insulin resistance." (PMID 40944254, 2025). "For every 500 nmol/L increase in RCF, GH2 increased and hPL decreased the risk of GDM, which is in line with their established roles in promoting insulin resistance and secretion, respectively." (PMID 40944254, 2025). "GH2 promotes maternal insulin resistance, whereas PRL promotes insulin secretion to compensate for the increase in maternal insulin resistance during pregnancy." (PMID 37049394, 2023). "This suggests that maternal obesity post-FA fortification may increase the risk of insulin resistance due to low PRL and hPL in the setting of higher GH2." (PMID 37049394, 2023). "Interestingly, GH2, which promotes insulin resistance, was lower in obese women in SCOPE (in line with lower PRL and hPL) but not in STOP." (PMID 37049394, 2023). "Interestingly, GH2 was also reported to increase pancreatic insulin secretion in human beta cells, although this role is less prominent than its role in promoting insulin resistance." (PMID 37049394, 2023). "Although we observed no changes in GH2 (promoter of insulin resistance), Folate:B12 ratio and Hcy were higher in STOP." (PMID 37049394, 2023). "Lower GH2 and hPL in STOP could imply reduced insulin resistance in the first trimester." (PMID 37049394, 2023).
preeclampsia (3 papers, 2012 to 2021). Preeclampsia is a hypertensive disorder of pregnancy that is characterized by new-onset hypertension with proteinuria presenting after 20 weeks of gestation, and depending on mild or severe forms may initially present with severe headache, visual disturbances, and hyperreflexia. "For example, genes involved in hormone regulation (i.e., CGB, CRH, INHA, and GH2), which have been previously shown to be key in the maintenance of pregnancy, show substantial overlap in preeclampsia studies." (PMID 26044726, 2015). "Women with new-onset GP in the absence of hypertension, particularly those with earlier onset, may exhibit a higher likelihood of progression to preeclampsia compared with women with a presumptive diagnosis of GH2." (PMID 34135442, 2021). "Without progression to preeclampsia until 12 weeks postpartum, GP or GH might be presumptive GP or presumptive GH2." (PMID 34135442, 2021). "► Reduced GH2-2/CSH1-2 transcripts retaining intron 4 only in preeclampsia without SGA." (PMID 22387044, 2012).
gestational diabetes mellitus (1 paper, 2012). "► Increased level of placental GH2 mRNA in gestational diabetes with LGA newborns." (PMID 22387044, 2012). "We investigated how the mRNA expression profile of placental GH2, CSH1 and CSH2 genes and their alternative transcripts correlates with maternal pre-eclampsia (PE) and/or gestational diabetes mellitus (GD)." (PMID 22387044, 2012).
HCMV infection (1 paper, 2021). "Genotype-specific IgG responses to gB1, gB2/3, gB4, gH1, and gH2 were tested in 25 women with non-primary HCMV infection." (PMID 33802390, 2021).
hypertrophic cardiomyopathy (1 paper, 2018). A condition in which the myocardium is hypertrophied without an obvious cause. "In GH2, a low temperature caused changes in proteins associated with hypertrophic cardiomyopathy (HCM), extracellular matrix (ECM)-receptor interaction, toxoplasmosis, and antigen processing (GH2-28 vs. GH2-16)." (PMID 30483139, 2018).
latent infection (1 paper, 2023). "We observed in a previous study that the gH1 genotype was predominant in infants with active CMV infection, while gH2 was more prevalent in children with latent infection." (PMID 37009289, 2023).
Obesity (1 paper, 2023). Accumulation of substantial excess body fat. "We analysed PRL, hPL and GH2 concentrations with respect to maternal age and obesity in SCOPE to determine if hormone concentrations are different in older women or those with obesity, or with a combination of the two in healthy pregnancy." (PMID 37049394, 2023). "The combined effects of maternal age and obesity on pregnancy hormones show that younger women with a healthy BMI had significantly higher PRL and hPL and lower GH2 in STOP compared to SCOPE." (PMID 37049394, 2023). "Maternal obesity: SCOPE women with obesity had lower PRL (−19%, [95% CI: 2 to 33%] p = 0.02), hPL (−21% [95% CI: 12 to 28%] p < 0.0001) and GH2 (−27%, [95% CI: 17 to 36%] p < 0.0001) compared to non-obese women." (PMID 37049394, 2023).
infection (5 papers, 2007 to 2025). The state of being infected such as from the introduction of a foreign agent such as serum, vaccine, antigenic substance or organism. "A GH2 gene thought to encode a mannosidase that acts on terminal β-1,4-mannans in hemicelluloses and N-linked glycoproteins was also expressed late in infection." (PMID 26332397, 2015).
metabolic disease (1 paper, 2020). A congenital disorder (due to inherited enzyme abnormality) or acquired (due to failure of a metabolically important organ) disorder resulting from an abnormal metabolic process. "The fungal glycoside hydrolases GH2 can specifically hydrolyze the β-glycosidic bond between d-glucuronidose and aglycon, and has important applications in the diagnosis and drug development of metabolic diseases." (PMID 32580753, 2020).
GH2 also shares sentences with these, for which no sentence is quoted: tumor (2 papers); acromegaly (1); adenoma (1); cancer (1); choriocarcinoma (1); deafness (1); encephalitis (1); glioma (1); Hearing impairment (1); lung adenocarcinoma (1); pituitary tumor (1); placental tumor (1); pneumonia (1); toxoplasmosis (1).